CDKL5 (cyclin dependent kinase like 5)
Diseases named in the same sentence as CDKL5 in open-access papers (continued):
Sharing a sentence is not in itself a finding about the gene and the disease.
Rett syndrome (91 papers, 2011 to 2025). A severe neurodevelopmental disorder affecting the central nervous system. "Chronic forniceal DBS has been reported to improve learning and memory in mouse models of Rett syndrome and CDKL5 deficiency disorders." (PMID 40004540, 2025). "Rett syndrome and CDKL5 deficiency disorder are much rarer, with estimated prevalences of ~1 in 10,000–15,000 and ~1 in 40,000–60,000 live births, respectively, and are typically caused by highly penetrant monogenic mutations." (PMID 41154630, 2025). "In Rett syndrome and CDKL5 deficiency disorder models, DBS strengthens hippocampal synaptic plasticity, reduces dentate inhibitory transmission or increases adult hippocampal neurogenesis that aids memory." (PMID 40004540, 2025). "A group of age-matched individuals (mean = 7.8 years; range = 1–17) with Rett syndrome, CDKL5 deficiency disorder, and typically-developing participants served as a comparison group." (PMID 36870948, 2023). "We have previously demonstrated the feasibility and tracking of evoked potentials to disease severity in Rett syndrome and CDKL5 deficiency disorder." (PMID 36870948, 2023). "Group-level comparisons revealed attenuated visual evoked potentials (VEPs) in participants with Rett syndrome (n = 43) and CDKL5 deficiency disorder (n = 16) compared to typically-developing participants." (PMID 36870948, 2023). "It is generally accepted that additional chromosome X is required for the survival of males affected by X-linked dominant mutations/disorders (e.g. Rett syndrome and CDKL5 deficiency)." (PMID 35248137, 2022). "Further genetic reports followed, describing CDKL5 variants as disease causing while also being genetically and clinically distinct from Rett syndrome." (PMID 35795799, 2022).
Rett syndrome (continued). "Downregulation of mTOR activity is thought to play an essential role in the pathogenesis of neurodevelopmental disorders such as Rett syndrome and Cyclin-Dependent Kinase Like 5 (CDKL5) deficiency disorder." (PMID 34204880, 2021). "The iPSCs generated from atypical Rett syndrome patients with a CDKL5 mutation exhibited a decrease in axon outgrowth, dendritic morphogenesis, and synapse formation in diseased neurons." (PMID 34360897, 2021). "From 2004 onwards, reports of CDKL5 as the causative gene of atypical Rett syndrome began to emerge." (PMID 32587608, 2020). "Two of the studies showed that 5-HT7R activation is able to reactivate mitochondrial dysfunction in mouse models of Rett syndrome and CDKL5 deficiency." (PMID 33348850, 2020). "In fact, the activation of 5-HT7R corrects molecular, electrophysiological, and behavioral alterations in mice models of neurodevelopmental disorders, such as Fragile-X syndrome, Rett syndrome, and CDKL5 deficiency disorder." (PMID 33348850, 2020). "Cyclin-dependent kinase-like 5 (CDKL5), a protein kinase, is the focus of this study, and its gene, CDKL5, has historically been linked to the atypical Rett syndrome." (PMID 32587608, 2020). "Thereafter, a mutation in CDKL5 was reported in individuals with the atypical Rett syndrome, a neurodevelopmental disorder, suggesting that CDKL5 plays an important regulatory role in neuronal function." (PMID 32587608, 2020). "Human CDKL5, linked to Rett syndrome, also localizes to cilia, and it impairs ciliogenesis when overexpressed." (PMID 29420175, 2018). "Although initially categorized as an atypical Rett syndrome, CDKL5 deficiency is now considered a distinct disorder, named CDKL5 deficiency disorder (CDD)." (PMID 30266824, 2018). "It is worth noting that in our study, MeHg induced a reduction in the expression level of CDKL5, a critical gene regulating neuronal morphogenesis which is mutated in the Hanefeld variant of Rett syndrome." (PMID 28756503, 2017). "For respiratory infections, females with the CDKL5 disorder had a slightly greater risk of having experienced pneumonia when compared to Rett syndrome (RR 1.24, 95 % CI 0.62, 2.51)." (PMID 27080038, 2016). "Initially described as an early onset seizure variant of Rett syndrome, the CDKL5 disorder is now considered as an independent entity." (PMID 27080038, 2016). "De novo mutations of the cyclin-dependent kinase-like 5 (CDKL5) gene are responsible for the Hanefeld variant of Rett syndrome (RTT), also referred to as CDKL5 disorder." (PMID 27965538, 2016). "Mutations in the cyclin-dependent kinase-like 5 (CDKL5) (NM_003159.2) gene have been associated with early-onset epileptic encephalopathies or Hanefeld variants of RTT(Rett syndrome)." (PMID 24564546, 2014). "Mutations in the cyclin-dependent kinase-like 5 gene (CDKL5) located in the Xp22 region have been shown to cause a subset of atypical Rett syndrome with infantile spasms or early seizures starting in the first postnatal months." (PMID 22867051, 2012).
Rett syndrome (continued). "Neurodevelopmental disorders (NDDs), including autism spectrum disorder (ASD), intellectual disability (ID), attention-deficit/hyperactivity disorder (ADHD), Rett syndrome, and CDKL5 deficiency disorder, represent a diverse group of conditions that affect approximately 1–3% of children worldwide." (PMID 41154630, 2025). "For example, comparison between parents of children with Down syndrome, Rett syndrome and CDKL5-associated disorder found that mothers of children with CDKL5-associated disorder, associated with high medical needs and poor neurodevelopmental prognosis, had poorest well-being." (PMID 38360654, 2024). "However, recent successful phase 3 trials in Rett syndrome and CDKL5 deficiency disorder argue against this nihilistic view." (PMID 38426491, 2024). "Interestingly CDKL5 mutations were confirmed in a girl in and boy patients who showed features of Rett syndrome." (PMID 38921700, 2024). "AEP amplitude correlated with severity in Rett syndrome and CDKL5 deficiency disorder." (PMID 36870948, 2023). "This is in stark contrast to other mouse models of neurodevelopmental disorders, such as those for Rett syndrome that show robust reductions in locomotor activity and those for CDKL5 deficiency disorder that exhibit consistent hyperactivity across similar behavioral tasks." (PMID 36848371, 2023). "Since CDKL5-deficiency may be considered as an atypical Rett-syndrome-like disorder, Rett-syndrome-like phenotypes associated with KSM may be even more frequent among males with neurodevelopmental disorders." (PMID 35248137, 2022). "Moreover, we show that a treatment with Fingolimod is able to prevent the structural defects described in hippocampal neurons from the mouse models of two neurodevelopmental disorders, namely Rett syndrome and Cdkl5 deficiency disorder." (PMID 32349283, 2020). "CDKL5 has historically been regarded as the causative gene of the atypical Rett syndrome." (PMID 32587608, 2020). "Whereas most of the RTT features presented by CDKL5 patients become evident when they get older, these patients lack the apparent normal development followed by regression that is usually considered a diagnostic criteria for Rett syndrome." (PMID 22779007, 2012). "Rapidly afterwards, in 2004, more reports described missense and frame-shift mutations in various positions of CDKL5 in individuals with clinical manifestations, ranging from atypical Rett syndrome (RTT) to autism." (PMID 31438497, 2019). "CDKL5 mutations have also been described in patients diagnosed with West syndrome, Lennox-Gastaut syndrome and atypical forms of Rett syndrome (RTT)." (PMID 27315173, 2016). "Cyclin-dependent kinase-like 5 (CDKL5) mutations are found in severe neurodevelopmental disorders, including the Hanefeld variant of Rett syndrome (RTT; CDKL5 disorder)." (PMID 27965538, 2016). "In the last years, the X-linked cyclin-dependent kinase-like 5 (CDKL5) gene has been associated with epileptic encephalopathies characterized by the early onset of intractable epilepsy, severe developmental delay, autistic features, and often the development of Rett syndrome-like features." (PMID 26849555, 2016).
Rett syndrome (continued). "In mouse models of intellectual disability disorders, we reported the beneficial memory effects of chronic forniceal DBS in Rett syndrome and Cdkl5 mutant mice." (PMID 40004540, 2025). "In fact, the disruption of neuronal migration and dendritic arborization resulting from Cdkl5 knockdown are rescued by wild-type Rac1 overexpression, further supporting the pathophysiological relevance of this complex interconnection in Rett syndrome." (PMID 34943902, 2021). "This analysis was critical to clarify the potential contribution of the nearby gene CDKL5, which is the main responsible for atypical Rett syndrome with early-onset seizures." (PMID 34884523, 2021). "Variants of or deletions in the X-linked gene CDKL5 have been reported to cause EEs such as X-linked infantile spasms, EIEE-2, autism spectrum disorders, and Rett-like syndrome, which is termed CDKL5 deficiency disorder (CDD)." (PMID 34163418, 2021). "The disease associated with CDKL5 mutation has recently been recognised as CDKL5 deficiency disorder (CDD) and has been distinguished from the Rett syndrome owing to its symptomatic manifestation." (PMID 32587608, 2020). "Our study adds to this notion, by analyzing the cellular effects of Fingolimod in two X-linked neurodevelopmental disorders, namely Rett syndrome (RTT) and Cdkl5 deficiency disorder (CDD)." (PMID 32349283, 2020). "Rett syndrome (RTT) and CDKL5 deficiency disorder (CDD) are two rare X-linked developmental brain disorders with overlapping but distinct phenotypic features." (PMID 31618813, 2019). "Gastrointestinal problems except for reflux were slightly less prevalent in CDKL5 affected females than Rett syndrome." (PMID 27080038, 2016). "Despite the apparent similarities in many of the clinical manifestations of the CDKL5 disorder and Rett syndrome, there are some differences in their occurrence and onset between the two disorders." (PMID 27080038, 2016). "It was also observed that there were differences in clinical features occurring in CDKL5 disorder and Rett syndrome, reinforcing the notion that CDKL5 is an independent disorder with its own distinctive characteristics." (PMID 27080038, 2016).
Rett syndrome (continued). "Later research however demonstrated that less than one quarter of CDKL5 cases would actually meet the criteria for this atypical form of Rett syndrome." (PMID 27080038, 2016). "The median age of scoliosis onset for females with the CDKL5 disorder (14 years, 95 % CI 12, -) was much later than in Rett syndrome (11 years, 95 % CI 10, 11.6)." (PMID 27080038, 2016). "On the other hand, lower respiratory tract infections such as pneumonia, were a little more likely to occur in CDKL5 affected females than in those with Rett syndrome." (PMID 27080038, 2016). "There were differences in the presentation of clinical features occurring in the CDKL5 disorder and in Rett syndrome, reinforcing the concept that CDKL5 is an independent disorder with its own distinctive characteristics." (PMID 27080038, 2016). "This large-sample study using a CDKL5 disorder specific database is the first to examine the comorbidities of the CDKL5 disorder in depth and to compare their occurrence with that of Rett syndrome." (PMID 27080038, 2016). "Data for the CDKL5 disorder and Rett syndrome were sourced from the International CDKL5 Disorder Database (ICDD), InterRett and the Australian Rett syndrome Database (ARSD)." (PMID 27080038, 2016). "On the other hand, the incidence of gastrostomy insertion was found to be slightly higher in the CDKL5 disorder than Rett syndrome." (PMID 27080038, 2016). "Our findings also suggest that autonomic dysfunction is less affected in CDKL5 disorder than in Rett syndrome." (PMID 27080038, 2016). "Aberrant neuron morphogenesis and synaptogenesis are associated with a number of brain disorders, including fragile-X mental retardation, Rett syndrome, Down syndrome, and CDKL5-related encephalopathy." (PMID 27822498, 2016). "Mutations in cyclin-dependent kinase-like 5 (CDKL5) cause early-onset epileptic encephalopathy, a neurodevelopmental disorder with similarities to Rett Syndrome." (PMID 24838000, 2014). "Although CDKL5 mutation screenings are generally performed in cohorts of Rett syndrome (RTT) or a variant of it, individuals with CDKL5 mutation present their unique characteristics." (PMID 24564546, 2014). "In particular, Rett syndrome, whose connection with CDKL5 has already been discussed, is characterized by a number of synaptic deficits." (PMID 22779007, 2012). "Mutations in CDKL5 are associated with a severe X-linked EE/DEE characterized by severe intellectual disability, generalized developmental delay, early-onset intractable seizures, infantile spasms, and Rett’s syndrome (RTT)-like features." (PMID 34842787, 2021).